WWOX (WW domain containing oxidoreductase)
Diseases named in the same sentence as WWOX in open-access papers (continued):
Sharing a sentence is not in itself a finding about the gene and the disease.
cancer (172 papers, 2004 to 2026). A tumor composed of atypical neoplastic, often pleomorphic cells that invade other tissues. "The WWOX gene, which has been implicated in various cancers, is also thought to play a role in sex development, although its involvement in 46,XY DSD remains poorly understood." (PMID 42082822, 2026). "WWOX, by tightly regulating HIF1α, is responsible for this mechanism in cancer cells consequently associated with cancer cell proliferation, invasiveness, patients’ survival, and treatment response." (PMID 41007296, 2025). "Allele loss at the WWOX locus has most commonly been observed in hormonal-regulated cancers such as breast, ovarian, and prostate cancers." (PMID 39473747, 2024). "The WWOX/Wwox gene and its encoded WWOX protein participate in cancer suppression and inhibition of AD progression." (PMID 38542478, 2024). "Defects in the gene WWOX are associated further with multiple types of cancer, i.a. hematopoietic malignancies." (PMID 38384455, 2024). "Mutations, deletions, loss of heterozygosity, and translocations of WWOX gene have been noted in many types of human cancers." (PMID 37897534, 2023). "WWOX, located within the chromosomal region 16q23.3–24.1, was initially recognized as a gene commonly subject to loss of heterozygosity in a variety of cancer types." (PMID 38203337, 2023). "The downregulation of WW domain-containing oxidoreductase (WWOX), a tumor suppressor gene, is associated with the tumorigenesis and poor prognosis of various cancers." (PMID 37324196, 2023). "Lastly, WWOX silencing-depended survival of cancer cells can be also associated with PRKG2 gene E2-induced expression." (PMID 35290621, 2022). "There appeared to be a dissimilarity in the regulation of Mesenchymal-to-Epithelial Transition (MET)-EMT,a which is implicated in cancer stemness; WWOX is thought to be an EMT inhibitor, AP-2γ an EMT enhancer, while AP-2α is thought to be an MET inducer." (PMID 34204827, 2021). "Dysregulation of WWOX not only leads to tumorigenesis and cancer progression, but also causes genome instability and treatment difficulties." (PMID 34948746, 2021). "Being located at a common fragile site with high frequencies of loss of heterozygosity and homozygous deletions, WWOX has been implicated in several types of human cancer, including breast, lung, liver, bone, and pancreatic cancers." (PMID 33916893, 2021). "The WWOX protein is involved in apoptosis and the mutation of WWOX is associated with many types of cancer." (PMID 34359791, 2021). "The WW domain-containing oxidoreductase gene (WWOX) was initially identified as a gene present in the chromosomal region 16q23.3-24.1 frequently affected by loss of heterozygosity (LOH) in various cancers." (PMID 33946771, 2021). "Somatic deletions and translocations affecting WWOX accompanied by loss of expression are frequent in multiple cancer types and associated with tumor progression, therapy resistance, and poor disease outcomes." (PMID 33255508, 2020). "Given its role in cellular metabolism, cell cycle checkpoint activation, and maintenance of genomic stability, dysregulation of WWOX has been implicated in cancer initiation and progression." (PMID 33129329, 2020). "Loss of this binding allows cancer growth, suggesting a novel mechanism of WWOX-mediated cancer suppression in vivo." (PMID 32764489, 2020). "Loss of WWOX, along with increased secretion of hyaluronan and hyaluronidases, frequently occurs in cancer cells at the late stage to facilitate metastasis." (PMID 31123603, 2019). "WWOX (WW domain containing oxidoreductase) expression loss is common in various cancers and characteristic of poor prognosis." (PMID 31275852, 2019).
cancer (continued). "Suppression of S14 phosphorylation in WWOX by Zfra (zinc finger-like protein that regulates apoptosis) peptide significantly reduces cancer growth in mice and restores memory loss in triple transgenic mice for AD." (PMID 31752354, 2019). "Later, when WWOX loss occurs in cancer cells, hyaluronidase production is then increased in the cancer cells to facilitate metastasis." (PMID 31123603, 2019). "WWOX protein mediates multiple signaling networks that suppress carcinogenesis through binding of its first WW domain to various cancer-associated proteins, i.e., p73, AP-2γ, and others." (PMID 30214895, 2018). "Overall, low levels of WWOX expression were associated with a poor clinical outcome, which suggested an important role of the protein in a broad range of human cancers." (PMID 30285739, 2018). "To mimic the natural course of events involving WWOX loss in cancer, we used siRNA knockdown of endogenous WWOX to study its role in paclitaxel-induced cell death in SKOV-3 and OVCAR-4 cell lines." (PMID 28749468, 2017). "A similar proportion of WWOX downregulation associated with aggressive phenotypes and poor prognosis has been observed in many cancers." (PMID 28426730, 2017). "Loss of WWOX allows nuclear accumulation of Smads and other transcription factors to promote cancer growth." (PMID 27845895, 2017). "Mutation and epigenetic silencing of the WWOX gene have been reported in various cancers, and the loss of WWOX expression is an important step in carcinogenesis." (PMID 27501229, 2016). "Hypermethylation of the promoter region of the WWOX gene has been reported as the cause of its down-regulation in various cancers." (PMID 25612104, 2015). "In previous studies, loss or deregulation of WWOX expression has been shown to be an important step in the development of various cancers and cancer cell lines." (PMID 25612104, 2015). "WWOX gene expression is altered in many cancers and in a recent work reduced WWOX expression has been associated with miR-134 expression in HNSCC." (PMID 25612104, 2015). "WWOX has been extensively studied for its role in cancer because it localizes to a common fragile site, FRA16D, a genomic region susceptible to chromosomal rearrangements." (PMID 24456803, 2014). "Complement C1q invokes WWOX activation via an unconventional pathway of apoptosis for causing cancer cell death." (PMID 27234396, 2013). "Loss of WWOX gene expression is frequently seen in malignant cancer cells due to promoter hypermethylation, genetic alterations, and translational blockade." (PMID 23459853, 2013). "Some studies have shown that the simultaneous loss of expression of FHIT and WWOX is frequent in several cancers." (PMID 16895604, 2006). "Mutation and deletion in the coding region of WWOX are rather infrequent in various types of cancer including HCC." (PMID 15266310, 2004). "Furthermore, both WWOX mutants exhibit defective DNA damage repair capacity, thereby probably predisposing carriers to cancer through genomic instability." (PMID 41124647, 2026). "This is the first study to indicate that the WWOX P252A variant is associated with cancer." (PMID 41124647, 2026). "Whether WWOX protein controls the transition between cancer susceptibility and AD resistance, or cancer resistance and AD progression has not been entirely delineated." (PMID 38542478, 2024). "Cancer promotion can occur through various processes, and numerous literature data indicate that reduction or loss of WWOX expression may regulate it by inhibiting programmed cell death and enhancing proliferation, migration, invasion, or genome instability." (PMID 36979157, 2023).
cancer (continued). "Moreover, literature data on in vivo studies suggest that WWOX in murine models has a crucial role in biological processes such as growth or metabolism, and that its loss leads to enhanced cancer stemness." (PMID 36979157, 2023). "The loss of WWOX expression in hyperplastic or cancer cells upon DDR induction may lead to senescence escape and consequently promote aberrant cell proliferation and genome instability." (PMID 37897534, 2023). "Moreover, WWOX depletion was found to be associated with enhanced inflammation and the cancer stemness phenotype." (PMID 36572673, 2022). "While pS14-WWOX supports the pathogenic progression toward AD severity and cancer growth and metastasis, the relationship between pT12 and pS14 in WWOX needs further elucidation, so as to increase our understanding of protein aggregation and the downstream TPC6AΔ in the protein aggregation cascade." (PMID 36498839, 2022). "Numerous scientific studies provide evidence that inhibition or loss of WWOX expression can promote cancer in a variety of ways: by inducing cell death resistance, proliferation, migration, invasion, metastasis formation, anaerobic glycolysis, or genome instability." (PMID 33946771, 2021). "We speculate that the variant allele 282 may affect the biological functions of WWOX, thereby making individuals susceptible to cancer." (PMID 34948746, 2021). "Therefore, the decreased expression of WWOX in 16q-loss cancers can contribute to the hyper-activation of Wnt pathways." (PMID 33808143, 2021). "Loss of the binding between WWOX and target proteins leads to increased cancer cell growth." (PMID 32764489, 2020). "Moreover, the expression of WWOX can lead to apoptosis, while defects in this gene are associated with multiple types of cancer." (PMID 30781701, 2019). "How loss of WWOX in cancer cells enhances their migration and metastasis was examined." (PMID 31123603, 2019). "Another cancer hallmark connected to the tumor suppressor gene WWOX is cell metabolism." (PMID 30619734, 2018). "Loss of heterozygosity (LOH) and alterations of WWOX gene have been shown in a variety of cancers." (PMID 27845895, 2017). "WWOX is known to regulate virus-associated immunodeficiency and various cancers, including HCC." (PMID 28426730, 2017). "Loss of WWOX expression because of gene deletions, loss of heterozygosity, chromosomal translocations, or epigenetic silencing is associated with poor prognosis in numerous types of cancer." (PMID 27977694, 2016). "WWOX, a tumor suppressor gene, is located in this region and is observed as a frequent loss due to heterozygosity or homozygous deletions in several human cancers." (PMID 26862731, 2016). "Loss of WWOX is associated with poor prognosis in numerous cancers and may result not only from deletions and translocations but also from epigenetic silencing by DNA methylation or mutations within its promoter." (PMID 27551470, 2015). "Nonetheless, the C1q/WOX1 signaling could be less efficient in cancers, as many advanced cancer cells are deficient in the wild type WWOX/WOX1." (PMID 19484134, 2009). "Therefore, loss of WWOX in human tumors might also lead to genomic instability, another hallmark of cancer." (PMID 30285739, 2018). "Notably, a tendency of reduced WWOX expression was observed in cancer adjacent liver tissue (P < 0.05), suggesting that loss of WWOX could be an early event in liver carcinogenesis." (PMID 29724996, 2018). "Moreover, previous studies have reported the effect of WWOX gene polymorphisms on human cancer susceptibility, and they have indicated that genotyping-related SNPs may efficiently predict the risk of cancers and other diseases." (PMID 27655721, 2016).
cancer (continued). "Therefore the pathways that WWOX normally participates in, and the nature of this participation, are of considerable interest for their likely causal and therapeutically targetable contribution to cancer cell biology." (PMID 26302329, 2015). "More in detail, chromosomal fragile sites FRA3B and FRA16D, carrying the FHIT and WWOX genes respectively, that are genes playing a major role in apoptosis, show correlated expression and association with failure of apoptosis in lymphocytes from cancer patients." (PMID 25860149, 2015). "Through this interaction, WWOX modulates cancer cell metabolism, which serves as an important prognostic factor." (PMID 41007296, 2025). "Given the central role of WWOX in restraining HIF1α-driven metabolic reprogramming, therapeutic strategies aimed at restoring WWOX function or inhibiting HIF1α activity hold significant potential to disrupt cancer metabolism and improve patient outcomes." (PMID 41007296, 2025). "Numerous studies have shown that WWOX expression is often lost or reduced in various cancers, including bladder, breast, liver, and nasopharyngeal cancers." (PMID 40006511, 2025). "The WWOX/HIF1A transcription ratio has emerged as a critical biomarker in cancer prognosis, offering valuable insights into tumour biology and informing therapeutic strategies." (PMID 41007296, 2025). "Our extensive analysis reinforces the tumour suppressor WWOX as a key modulator of cancer metabolism through direct physical interaction with HIF1α via its WW domain, inhibiting its transactivation potential and promoting its degradation." (PMID 41007296, 2025). "Additional pathways such as cell cycle regulation, xenobiotic metabolism by cytochrome P450 (CYP2C9), and nitrogen metabolism can influence cancer progression, although their direct links to the WWOX/HIF1A ratio require further investigation." (PMID 41007296, 2025). "Our studies have established that the WWOX/HIF1A ratio is a key regulatory axis in cancer biology, orchestrating cellular differentiation, metabolic reprogramming, invasiveness, EMT regulation, angiogenesis, and immune evasion in multiple tumour types." (PMID 41007296, 2025). "WWOX is a gene that plays a key role in regulating cellular processes related to maintaining homeostasis and protecting against cancer, through interactions with many proteins and signalling pathways." (PMID 41007296, 2025). "WWOX is recognized as a crucial tumour suppressor, not only inhibiting tumour formation but also regulating essential pathways involved in cancer progression." (PMID 41007296, 2025). "Our findings highlight that a high WWOX/HIF1A ratio correlates with favourable prognosis across multiple cancers by promoting oxidative metabolism, enhancing DNA repair, maintaining ECM integrity, and supporting immune surveillance." (PMID 41007296, 2025). "This review provides a comprehensive overview of the structure, function, and role of WWOX in tumors, emphasizing its critical regulatory effects on cancer." (PMID 41228229, 2025). "By examining and evaluating the distinct prognostic associations across diverse malignancies and by highlighting the role of metabolic, ECM, and EMT pathways, we emphasize the potential of the WWOX/HIF1A ratio as a valuable biomarker for cancer prognosis." (PMID 41007296, 2025). "Our previous findings first demonstrated that WWOX loss or reduction significantly contributes to cisplatin resistance of TNBC cells and provides a survival advantage to cancer cells." (PMID 39473747, 2024). "We reported that the more strongly endogenous WWOX binds intracellular protein partners, the more weakly the cancer cells can grow in vivo." (PMID 38542478, 2024). "Most cancer cells derived from breast, lung, prostate, and other organs have alterations in the WWOX gene." (PMID 38542478, 2024). "We reported that when endogenous WWOX strongly binds intracellular protein partners in cancer cells, the cells cannot grow effectively in vivo." (PMID 38542478, 2024).
cancer (continued). "The stronger the binding of WWOX with target proteins, the better the suppression of cancer growth and retardation of neurodegeneration." (PMID 38542478, 2024). "Restoration of the WWOX gene and the resulting protein in cancer cells blocks their growth in vivo and in vitro." (PMID 38542478, 2024). "The principal finding of that initial study suggested that reduced WWOX expression, which commonly occurs in cancers, results in resistance to cisplatin." (PMID 39473747, 2024). "Zfra-activated Hyal-2+ CD3- CD19- Z cells in the spleen, via Hyal-2/WWOX/Smad4 signaling, are potent in cancer suppression." (PMID 38542478, 2024). "In LC H1299 cells, inhibition of RUNX2 and its target gene MMP-9 by WW domain-containing oxidoreductase (WWOX) significantly suppressed cancer cell migration and invasion." (PMID 37766868, 2023). "WW domains are responsable for the interaction of WWOX with a large set of protein partners involved in several cancer-related molecular pathways." (PMID 37248434, 2023). "WWOX has been shown to play a crucial role not only in cancer development but also in various other cellular processes." (PMID 38203337, 2023). "Recent molecular and clinical analyses of WWOX functions have emphasized its role in the modulation of signaling pathways related to cancer promotion, metabolism, CNS development, and neurological diseases." (PMID 36979157, 2023). "WW domain-containing oxidoreductase (WWOX), which is frequently lost in several cancers, sensitizes EOC to paclitaxel via ERS-induced apoptosis, and is predictive of clinical outcomes in patients." (PMID 37817482, 2023). "We have previously reported that EVO activates WW-domain-containing oxidoreductase (WWOX) to exert its anti-cancer efficacy." (PMID 37046995, 2023). "Abnormal transcription and low expression of WWOX have been reported in several cancers with an aggressive, poor prognosis." (PMID 37324196, 2023). "Delineation of WWOX-regulated signaling pathways upon DDR activation will gain a greater understanding of the pathogenesis of cancers, age-related diseases and early postnatal lethality due to WWOX loss in humans." (PMID 37897534, 2023). "In light of the findings, Zfra4-10-mediated suppression of cancer and AD is due, in part, to an enhanced binding of endogenous WWOX and its binding partners." (PMID 35883580, 2022). "In contrast, pS14-WWOX is accumulated in the lesions of cancers and AD brains, and suppression of WWOX phosphorylation at S14 by a short peptide Zfra abolishes cancer growth and retardation of AD progression." (PMID 35883580, 2022). "WWOX, as a fragile gene, is likely to undergo deletions and rearrangements that make it a prominent candidate for diverse cancers." (PMID 35460704, 2022). "In parallel, synthetic Zfra4-10 or WWOX7-21 peptide strengthens the binding of endogenous WWOX with intracellular protein partners leading to cancer suppression." (PMID 35883580, 2022). "Among these mutations, deletion of the WW domain-containing oxidoreductase (WWOX) gene is one of the most active and common fragile sites (CFSs) involved in cancer, has been identified." (PMID 36572673, 2022). "Supporting evidence shows that the more strongly WWOX binds intracellular protein partners, the weaker is cancer cell growth in vivo." (PMID 35883580, 2022). "ACK1 (activated CDC42 kinase 1) is a serine/threonine-protein kinase that contributes to cancer migration, survival, and proliferation via regulating WWOX and AKT1." (PMID 35600868, 2022). "Suppression of WWOX phosphorylation at S14 by Zfra4-10 peptide results in significant reduction in cancer growth in mice, and enhanced restoration of memory loss and mitigation of AD-like symptoms in triple transgenic (3xTg) mice." (PMID 35883580, 2022).